CXCL10 (C-X-C motif chemokine ligand 10)
Diseases named in the same sentence as CXCL10 in open-access papers (continued):
Sharing a sentence is not in itself a finding about the gene and the disease.
influenza (continued). "We infected both C57BL/6 and STAT1−/− mice with influenza or PBS control and then measured the relative expression of Mx1 and the chemokine CXCL10." (PMID 38750107, 2024). "We next assessed expression levels of various cytokines and chemokines (i.e., IFNB1, IFNL1, IFNL2/3, IFIT1, IFIT3, OAS1, MX1, IL‐6, CXCL10, and IFITM1) which were triggered by influenza and OC43 virus infections alone or together by qPCR." (PMID 38556468, 2024). "In our study, we found increased expression of CCL2, CCL3, CXCL9, and CXCL10 in the heart following PR8, pH1N1, or H3N2 strains of influenza infection." (PMID 38750107, 2024). "CXCR3 ligands CXCL9, CXCL10 and CXCL11 are highly expressed in the lung in response to influenza as well as M. tuberculosis infection." (PMID 37896952, 2023). "It has been reported that people infected with influenza have higher levels of cytokines stimulated by type I IFNs (such as IL-6 and IFN-γ), and the chemokines IP-10 (also known as CXCL-10) and MCP-1 (CCL2)." (PMID 35154087, 2021). "During influenza infection, secretion of CXCL9 and CXCL10 from the inflamed epithelium recruits CD8 T cells expressing CXCR3 chemokine receptors." (PMID 32817719, 2020). "Interestingly, plasma concentrations of CXCL10 have been previously reported at high levels in SARS-CoV-1, respiratory syncytial, and influenza infections, and significantly associated with a higher risk of death in ARDS associated with A/H1N1 influenza infection." (PMID 33138839, 2020). "Influenza infection induces a variety of inflammatory cytokines and chemokines such as IL-6, IL-8, TNFα, CCL2, CCL5, CXCL10, and recruitment of neutrophils and macrophages to clear the virus." (PMID 31159430, 2019). "Influenza infection induced a variety of inflammatory cytokines such as IL-1β, IL-6, TNFα, IL-8, CCL2, CCL5, and CXCL10 from epithelial and immune cells." (PMID 30337919, 2018). "Influenza infection also induces the production of such cytokines as TNFa, IL-1, IL-6, and the mononuclear cell attractant chemokines: CCL-3, CCL-4, CCL-5, CXCL9, CXCL10, and CXCL11 in human monocytes, epithelial cells, and rat alveolar or murine macrophages." (PMID 30037133, 2018). "CXCL10 and IL6 are known to be highly elevated after influenza infection, and the previous cytokine-chemokine analysis indicated that plasma CXCL10 was correlated with viral loads." (PMID 27088501, 2016). "CXCL10/IP-10 and CXCL9/MIG are stimulated by IFN-γ, which together orchestrate the Th1 cellular immune response, known to be important for virus control in influenza infection." (PMID 22022504, 2011). "PBMCs in seasonal influenza patients were activated and expressed cytokines ex vivo (e.g. IL-6, CXCL8/IL-8, CCL2/MCP-1, CXCL10/IP-10, CXCL9/MIG); their ‘responsiveness’ to stimuli was shown to change dynamically during the illness course." (PMID 22022504, 2011). "Our finding of a strong adaptive-immunity related cytokine response (e.g. CXCL10/IP-10, CXCL9/MIG, IL–17A; and IFN-γ) in seasonal influenza but a relatively suppressed response in severe pH1N1 pneumonia is striking." (PMID 22022504, 2011). "Notably, CXCL10, CXCL9, and CXCL11 had previously been found to be upregulated in human nasal epithelial cells after infection with human influenza H3N2." (PMID 41239423, 2025). "Interestingly, the only cytokine overlapping between the severe influenza profile and the CFS profile is CXCL10 (IP-10), which is elevated in both conditions." (PMID 40640868, 2025). "The expression of interferon response genes STAT1, STAT2, Mx1, OASL2, ISG15, chemokines CCL2, CCL3, CXCL9 and CXCL10, and the frequency of neutrophils (CD45+CD11b+Ly6G+) and CD4+ T cells (CD45+CD4+) were all significantly increased in influenza-infected mice when compared to vehicle controls." (PMID 38750107, 2024).
influenza (continued). "Higher CXCL10 levels after both IIV and LAIV influenza vaccination have previously been reported." (PMID 36670200, 2023). "Notably, when compared with the seasonal influenza group, the Th1-related CXCL10/IP-10 and CXCL9/MIG, and the Th17-related IL-17A were markedly suppressed in cases of severe pH1N1 pneumonia (2–27 times lower; P−values <0.01)." (PMID 22022504, 2011). "Overall, the most prominent induction was observed for CXCL-10/IP-10 regardless of influenza subtype, and with > 1,000-fold increase at peak induction." (PMID 22185562, 2011). "Rsad2, Cxcl10, Saa3, Irf7, and Il1rn, which have been reported in influenza, whereas the role of LCN2 in influenza was still unknown." (PMID 35495713, 2022). "Interestingly, plasma CXCL10 was induced by IAV infection more rapidly than in the BALF, suggesting an extrapulmonary site of production, such as the liver, which has been shown to become activated during influenza infection." (PMID 30138446, 2018). "Furthermore, transcription of the Cxcl10 gene, which encodes the principal CXCR3 ligand in influenza-infected lungs, was not affected by IL-4C, suggesting that IL-4-driven CXCR3 upregulation in both CD44hi and CD44low CD8 T cells caused such cells to accumulate in inflamed lungs." (PMID 38037190, 2023). "In addition, inactivation of influenza by UV did not abolish the influenza viruses-stimulated CXCL10 secretion by AM, which is different from studies with human monocyte-derived macrophages and with human alveolar type II epithelial cells isolated from the same donors (and data not shown)." (PMID 22396727, 2012). "In addition to the known components of the hypercytokinemia response in influenza infection (IL6, IL29, CXCL10, CCL4) we have identified several other genes that our model can predict across species, which could be playing roles in initiating and/or sustaining this response." (PMID 22074594, 2011).
rheumatoid arthritis (104 papers, 2005 to 2026). A chronic, systemic autoimmune disorder characterized by inflammation in the synovial membranes and articular surfaces. "In this context, it has been indicated that CXCL10 is also associated with disease activity and the perseverance of rheumatoid arthritis." (PMID 38541021, 2024). "TNF-alpha, IL-1beta, CXCL8, and CXCL10 levels have been linked with ankylosing spondylitis and crystal, psoriatic and rheumatoid arthritis." (PMID 35153741, 2021). "In particular, serum levels of CXCL-10 were elevated in patients suffering from a rheumatoid arthritis and expression of CXCL-10 caused the recruitment of inflammatory cells and is involved in bone erosion in inflamed joints." (PMID 30305140, 2018). "It has been reported that elevated plasma chemokine level was discovered in RA patients, and CXCL10 can be served as a diagnostic biomarker for active rheumatoid arthritis." (PMID 32802866, 2020). "High circulating levels of CXCL10 in the plasma of ueRA patients and the association with the clinical disease activity suggests that CXCL10 may serve as a disease activity marker in early rheumatoid arthritis." (PMID 28148302, 2017). "For instance, in rheumatoid arthritis, similar to pSS, CXCL10 increased the migration of inflammatory cells mediated through CXCR3 binding on CD4-positive T helper cells." (PMID 39436967, 2025). "CD109 facilitates the activation and recruitment of leukocytes by promoting the production of CXCL-9 and CXCL-10 in rheumatoid arthritis FLSs." (PMID 39990858, 2024). "The cytokine–cytokine receptor interaction pathway and the increased expression of Cxcl9 and Cxcl10 are related to the development of rheumatoid arthritis." (PMID 35911717, 2022). "TYMP also enhanced C-X-C motif chemokine 10 (CXCL10) production in an in vitro model of rheumatoid arthritis, while this chemokine is also described as a urinary biomarker of ABMR." (PMID 35327371, 2022). "CXCL10 expression level is elevated in different diseases such as rheumatoid arthritis and psoriatic arthritis." (PMID 35628333, 2022). "In the pathological bone destruction of rheumatoid arthritis, the reciprocal amplification of CXCL10 and RANKL was reported to promote osteoclast differentiation." (PMID 36078141, 2022). "For example, MDX-1100, a biologic that targets CXCL10, has already shown efficacy for treatment of rheumatoid arthritis in phase II clinical trials." (PMID 31631836, 2019). "In this regard, CXCL10 can be blocked in vivo by Eldelumab, a humanized mAb that has been used in clinical trials for rheumatoid arthritis and inflammatory bowel diseases." (PMID 31699153, 2019). "First, we compared serum CXCL10 expression in patients with PsA and in healthy control subjects, as well as SF CXCL10 expression in patients with PsA, OA, rheumatoid arthritis (RA), and gout." (PMID 27964744, 2016). "Because elevated serum levels of CXCL10 have been observed in many diseases including rheumatoid arthritis, systemic lupus erythematosus, systemic sclerosis, and HIV infection, it probably has no utility as a specific diagnostic marker for SCLS." (PMID 25405070, 2014). "All three groups of autoimmune arthritis patients (ankylosing spondylitis, psoriatic arthritis and rheumatoid arthritis) had significantly increased synovial CXCL10 levels compared with crystal arthritis patients." (PMID 16846531, 2006). "Since TNF-α and IL-1β are implicated in arthritis, synovial concentrations of CXCL8 and CXCL10 were compared in patients suffering from crystal arthritis, ankylosing spondylitis, psoriatic arthritis and rheumatoid arthritis." (PMID 16846531, 2006). "Moreover, high levels of inflammatory/arthrogenic factors, including cytokines (TNF-α, IL-6, IL-7, IL-15, and BAFF) and chemokines (CCL-2, CCL-5, and CXCL-10) have been reported in the serum and/or synovia of rheumatoid arthritis patients." (PMID 38720890, 2024).
rheumatoid arthritis (continued). "Notably, CSA is a robust inhibitor of CXCL10-induced NFATc1 activation, a mechanism by which CXCL10 regulates the recruitment of inflammatory cells in rheumatoid arthritis." (PMID 35536669, 2022). "Indeed, a clinical trial was performed to evaluated rheumatoid arthritis treatment with an anti-CXCL10 blocking antibody, which showed partial improvement of inflammatory responses." (PMID 35393946, 2022). "The same conclusions were drawn in a related study on the microarray analysis of gene expression in rheumatoid arthritis joints performed using cDNA microarrays and laser microdissection: CXCL9 and CXCL10 upregulation in the synovial lining associated with inflammation." (PMID 35734177, 2022). "Whilst plasma is a minimally invasive sample of choice for biomarker-based testing, the measurement of systemic CXCL10 concentrations could be confounded in certain scenarios (for example, those with an inflammatory component such as rheumatoid arthritis." (PMID 34200333, 2021). "In addition, CXCL10 and its receptor are increased in many kinds of chronic inflammatory arthritis, especially in rheumatoid arthritis (RA), which can be produced by infected tissue together in vivo and in vitro." (PMID 31214025, 2019). "To evaluate where CXCL10 identifies a specific cause of CKD, such as immune-mediated causes of renal injury from systemic lupus erythematosus, rheumatoid arthritis, antineutrophil cytoplasmic antibody (ANCA)-positive vasculitis, we evaluated which CKD categories had high abundance of urinary CXCL10." (PMID 31013714, 2019). "While rheumatoid arthritis and AD have distinct etiologies, our body of work indicates that CXCL10 or CXCR3 may be promising targets for treating chronic itch." (PMID 31631836, 2019). "The expression of CXCL9 and CXCL10 is also increased in the joints of patients with rheumatoid arthritis suggesting that these chemokines may contribute to the joint pathology associated with the disease." (PMID 24947159, 2014). "Similar evidence has been provided for a correlation between plasma HIV RNA levels and sCD163, and the interrelationship between sCD163 and CXCL10 identified in this study has also been noted in rheumatoid arthritis – suggesting common activation pathways for these molecules." (PMID 25544986, 2014). "Taking the results of this study into consideration in parallel with the studies on rheumatoid arthritis, the CXCL10/CXCR3 pathway may be a candidate as a therapeutic target in human IIMs." (PMID 24939012, 2014). "The CXCL10/CXCR3 and CXCL13/CXCR5 axes are associated with disease activity in several autoimmune diseases including rheumatoid arthritis (RA), systemic lupus erythematosus (SLE) and adult onset Still’s disease." (PMID 29116188, 2017). "Serum samples from 49 patients diagnosed with pSS, 33 patients with rheumatoid arthritis (RA), and 30 healthy controls (HCs) were collected for measurements of CXCL9, CXCL10, CXCL11, and CXCR3." (PMID 38900301, 2024). "Our data suggest the potential role of cytokine CXCL10 in COM development and maintenance, which is also involved in the activity of its concomitant disease, rheumatoid arthritis." (PMID 38541021, 2024). "Other researches showed that CXCL10 was recommended as a disease activity marker of early rheumatoid arthritis, as well as serum CXCL13 level was closely related to rheumatoid arthritis and rheumatoid factor levels." (PMID 37393391, 2023). "In murine arthritis, tofacitinib reduces levels of plasma IL-6 and CXCL10 (IFN-γ–induced protein 10), while in rheumatoid arthritis (RA), it lowered IL-6 in one clinical trial but decreased CXCL10 in another." (PMID 35943798, 2022). "Murine and translational studies suggested that CXCR3 and CXCR6 are key elements for effector T cells to migrate into the joints in rheumatoid arthritis, and MDX-1100, anti-CXCL10 monoclonal antibody, showed clinical efficacy in rheumatoid arthritis." (PMID 35413951, 2022).
rheumatoid arthritis (continued). "More recent evidence has demonstrated increased levels of CXCL8, CXCL9, CXCL10, and CCL20 in rheumatoid arthritis, indicating the importance of chemokines in inflammatory bone diseases." (PMID 33510341, 2021). "The CXCL10/CXCR3 chemokine axis and RANKL/OPG signaling potentially contribute to joint inflammation and bone destruction during rheumatoid arthritis." (PMID 32381074, 2020). "Transfection of miR-20a mimic reduced the release of IL-6, CXCL10, and IL-1β, as well as TNF-α by rheumatoid arthritis fibroblast-like synoviocytes." (PMID 33584204, 2020). "Ongoing phase II clinical trials MDX-1100-anti-CXCL10, indicated here by PPI analysis in closed pyometra, have been conducted in inflammatory bowel disease and rheumatoid arthritis." (PMID 26222498, 2015). "One of them, fully human anti-CXCL10 antibody MDX-1100 (aka BMS-936557; Bristol Myers Squibb) has demonstrated efficacy in Phase II clinical trials involving patients with rheumatoid arthritis and ulcerative colitis." (PMID 25879435, 2015). "Currently, clinical trials using CXCL10 antibody (MDX-1100), are looking promising in patients with ulcerative colitis and rheumatoid arthritis, promoting investigations of the role of CXCR3 in chronic colitis." (PMID 24992040, 2014). "Mast cells preferentially express CXCR3 protein in patients with rheumatoid arthritis and, importantly, this expression is accompanied by elevated level of CXCL9 and CXCL10." (PMID 24278169, 2013). "Further studies are needed in animal models to explore the therapeutic potential of CXCR3- or CXCL10-antagonists, with the ultimate goal of offering new clues for immune intervention in Th1-mediated diseases such as JIA and rheumatoid arthritis." (PMID 15743470, 2005). "For instance, elevated CXCL10 expression was observed in patients with interstitial lung disease (ILD), leukopenia, and anemia; JAK2 expression differed in rheumatoid arthritis comorbidity; IFIH1 expression also showed differences in those with Raynaud's phenomenon and ILD." (PMID 41929488, 2026). "Furthermore, clinical-grade fully human anti-CXCL10 monoclonal antibodies, such as MDX-1100 (eldelumab), have already been developed and tested in Phase II clinical trials for rheumatoid arthritis and ulcerative colitis." (PMID 41516196, 2025). "Studies showed that various chemokines participated in RJD pathogenesis: rheumatoid arthritis patients exhibit increased levels of plasma CCL2, CCL3, CCL4, and CXCL10 and psoriatic arthritis patients also exhibited high values of CCL2 and CXCL10." (PMID 38622714, 2024). "T cell CXCR3 and its ligands CXCL9 and CXCL10 as well as CCR5 and its ligands CCL3 and CCL5 are expressed at higher levels in disorders where Th1 immune responses predominate such as multiple sclerosis and rheumatoid arthritis." (PMID 36670847, 2023). "Another possibility is that in the pathogenesis of rheumatoid arthritis, CXCL10 acts on CXCR3 rather than TLR4 on macrophages or T lymphocytes to activate ERK, thereby increasing the ability of macrophages or T lymphocytes to migrate." (PMID 37048082, 2023). "The proinflammatory cytokines such as IL-1β, IL-6, TNF, CXCL9, CXCL10, and IFN-γ participate in the pathology of several chronic inflammatory diseases including rheumatoid arthritis, coronary diseases, cerebral malaria, tegumentary leishmaniasis, and Chagas diseases." (PMID 32385802, 2020). "Moreover, CXCL10 and CXCR3 expression is also increased in the synovial membrane of rheumatoid arthritis patients." (PMID 24939012, 2014). "C-X-C motif chemokine 10 (CXCL10) is an inflammatory chemokine and a key molecule in the pathogenesis of rheumatoid arthritis (RA)." (PMID 33387195, 2021). "IFN-gamma inducible protein-10 (CXCL10), a member of the CXC chemokine family, and its receptor CXCR3 contribute to the recruitment of T cells from the blood stream into the inflamed joints and have a crucial role in perpetuating inflammation in rheumatoid arthritis (RA) synovial joints." (PMID 21708014, 2011).
rheumatoid arthritis (continued). "In rheumatoid arthritis (RA), high CXCR3 expression on mast cells is associated with CXCL9 and CXCL10 expression in synovial fluid from RA patients but not in traumatic arthritis or osteoarthritis patients." (PMID 36275816, 2022). "Moreover, studies in patients with rheumatoid arthritis (RA) showed that fibroblast-like synoviocytes (FLS) constitutively express CCR2, CCR5, CXCR3,and CXCR4; in addition, stimulation with CCL2, CXCL12, CXCL9, and CXCL10 enhances FLS migration and proliferation." (PMID 28883822, 2017).